CRP (C-reactive protein)
Diseases named in the same sentence as CRP in open-access papers (continued):
Sharing a sentence is not in itself a finding about the gene and the disease.
cancer (continued). "Compared with the risk of cancer of patients with low average cumulative CRP and MetS-Z, patients with high value had a significantly increased risk (hazard ratio = 1.54, 95% CI = 1.30, 1.83)." (PMID 38386717, 2024). "Cancer-associated systemic inflammation is characterized by a rapid increase in the production of acute-phase proteins CRP, NLR, and PLR, represented in CRC." (PMID 39337548, 2024). "A comprehensive meta-analysis included 10 studies with 2252 patients and demonstrated that an elevated CRP level was strongly associated with worse cancer-specific survival (CSS) in UTUC patients who underwent RNU." (PMID 39272712, 2024). "Logistic regression analyses were used to compute Odds ratio (OR) and 95%CIs for the association between serum CRP and the incidence of COVID-19 pneumonia in cancer patients." (PMID 38215120, 2024). "Joint analysis of IL-1β and CRP levels was characterized by high diagnostic usefulness in predicting the risk of cancer cachexia (AUC = 0.956; p < 0.0001)." (PMID 38610941, 2024). "This contributes to chronic systemic inflammation with enhanced concentrations of circulating cytokines such as CRP and IL-6 and adipokines, which is associated with cancer progression and poor survival in patients with CC." (PMID 38172335, 2024). "For instance, systemic inflammatory responses, such as elevated C-reactive protein levels, have been found to play a crucial role in predicting patient outcomes, with approximately 20% of cancers globally linked to infections and inflammatory reactions." (PMID 39877368, 2024). "We are among the first to employ MR analysis to investigate the association between CRP and EC subtypes, and our results suggest that the impact of inflammatory biomarkers on EC risk varies by cancer type." (PMID 39809220, 2024). "Elevated CRP, increased neutrophils, and raised platelets are associated with increased risk of cancer." (PMID 39054298, 2024). "Heightened levels of CRP prove to be a valuable indicator for identifying patients' susceptibility to cardiovascular disease and specific cancers, offering guidance for therapeutic interventions." (PMID 39376593, 2024). "CRP is an acute phase reactant that is indicative of cancer‐related inflammation and associated with advanced disease and aggressiveness." (PMID 35781808, 2023). "Some works suggest the combined dosage of CRP with other serum biomarkers increased the diagnostic accuracy for cancer detection." (PMID 36938312, 2023). "In concordance with our results, previous studies have shown that reduced food intake, loss of appetite and inflammation measured as elevated CRP-level is a risk factor for over all-survival in patients with cancer." (PMID 37880704, 2023). "The reported increased serum levels of acute phase proteins such as CRP have previously been shown to contribute to the tumour itself and cancer-associated systemic inflammation." (PMID 37686583, 2023). "Preoperative inflammatory markers, such as Glasgow prognostic score, modified Glasgow prognostic score and C-reactive protein to albumin ratio, were shown to be associated with prognosis in patients undergoing pancreatectomy for cancer." (PMID 37322265, 2023). "More recently, the C-reactive protein (CRP) to albumin ratio (CAR) has been demonstrated to be associated with survival outcomes in cancer patients." (PMID 37509622, 2023). "Another epidemiological study reported that individuals in the highest quintiles of omega-6 fatty acids exhibited lower concentrations of CRP and reduced incidences of cardiovascular disease, cancer, and all-cause mortality." (PMID 38004181, 2023). "After treatment, the upregulation of serum inflammatory markers C-reactive protein (CRP) and interleukin-6 (IL-6) predicts a high risk of cancer recurrence and patient death." (PMID 36835173, 2023). "CRP was positively associated with depressive symptoms only among women who reported high levels of cancer-related stress in a longitudinal study of women with breast cancer." (PMID 36717689, 2023).
cancer (continued). "In the literature, the accepted cutoff value of CRP for investigation of several cancer-associated events was reported as 10 mg/L." (PMID 36793395, 2023). "The multivariate analysis also showed that elevated CRP was associated with an increased risk of cancer." (PMID 36440611, 2023). "Cachexia is often associated with cancer and a systemic inflammatory state, with high pro-inflammatory markers such as C-reactive protein (CRP)." (PMID 37630580, 2023). "The IL-6-driven acute phase response protein CRP (C-reactive protein) was similarly associated with plasma IL-6 and poor OS in all three cancer types." (PMID 36599350, 2023). "Previous studies have found increased CRP concentrations associated with the risk of cardiovascular disease, psoriatic arthritis, type 2 diabetes, and cancer." (PMID 36624433, 2023). "The linear model linking the TS relative to baseline TS, to CRP production translates to the fact that the inflammatory status associated with the malignant tumor stimulates inflammatory cytokines that in turn activate the hepatocytes to release CRP." (PMID 38001689, 2023). "Cancers are usually associated with chronic inflammation and CRP is a prognostic marker for some cancers." (PMID 37794336, 2023). "The limited evidence from clinical samples found that a higher concentration of C-reactive protein, a proinflammatory marker, was associated with mortality risk among cancer survivors." (PMID 36883906, 2023). "We also found that among four biomarkers associated with cancer cachexia, the combinations of cachexia and CRP, PTX‐3, or OPN expression levels were associated with patient prognosis." (PMID 37712645, 2023). "Elevated levels of all three markers were associated with risk of cancer within 3 months: CRP (odds ratio (OR) 4.41, 95% confidence interval (CI) 2.86–6.81), IL‐6 (OR = 2.89, 1.91–4.37) and YKL‐40 (OR = 2.42, 1.59–3.66)." (PMID 36440611, 2023). "Unadjusted higher levels of CRP, IL-6, and IL-8 were associated with greater frailty in the non-cancer control group." (PMID 37213604, 2023). "Baseline dNLR and CRP have also been shown to be independently associated with cancer-specific survival in further analysis, suggesting the specificity of these two parameters in predicting tumor-related causes of death." (PMID 36673123, 2023). "The increase in IL-6 and CRP is typical for inflammaging, and both proteins are also elevated in cancer and their levels are associated with tumor progression and prognosis." (PMID 37895144, 2023). "CRP has been reported to be associated with cancer grade and poorer prognosis in not only ATC but also DTC." (PMID 37444559, 2023). "The association between cancer and inflammation is known for years, and the mechanisms behind CRP rise are well understood." (PMID 38037003, 2023). "CRP stands as one of the most extensively studied inflammatory biomarkers linked to cancer cachexia, even serving as a proposed diagnostic criterion." (PMID 37755304, 2023). "Elevated CRP is associated with an increased risk of cardiovascular disease and can predict multiple forms of cancer, including lung, breast, and prostate cancers; type 2 diabetes; and earlier mortality." (PMID 38064253, 2023). "Additional studies are therefore needed to confirm the usefulness of serial CRP measurements over a single measurement for cancer risk prediction in the general population." (PMID 37019514, 2023). "Exercise intervention studies have reported results on the reduction of inflammatory biomarkers associated with cancer including C-reactive protein (CRP), interleukin-6 (IL-6) and tumor necrosis factor-α (TNF-α)." (PMID 35779184, 2023). "An evaluation of the levels of several proteins associated with inflammation: IL-6, D-dimer and C-reactive protein enabled the association of high levels of IL-6 with a 40% increase in cancer risk." (PMID 37491285, 2023).
cancer (continued). "A previous study of patients referred to another Diagnostic Outpatient Clinic in Denmark also found that high CRP and soluble urokinase plasminogen activator receptor were associated with cancer diagnosis." (PMID 36440611, 2023). "Locally or systemically elevated IL-6 levels have been reported to be associated with increased CRP concentrations in various cancers." (PMID 37081512, 2023). "C-reactive protein (CRP), a very important biomolecule of the immune system, is a clinical biomarker closely associated with cancer and cardiovascular and neurological diseases." (PMID 36771930, 2023). "Elevations in CRP level have been implicated as a useful marker to identify patients at risk for cardiovascular disease and certain cancers, and to guide therapy in a context-dependent manner." (PMID 37564640, 2023). "Elevated CRP levels are also correlated with an increased risk of cancer types such as liver, lung, colorectal, and breast cancer." (PMID 37755304, 2023). "This research investigated how SMU is associated with CRP—a biological marker of inflammation linked with chronic illnesses such as cardiovascular disease and cancers." (PMID 38064253, 2023). "Logistic regression analysis identified the following factors as associated with cancer cachexia: ghrelin (p = 0.041), CRP (p = 0.030), PTX‐3 (p = 0.045), and OPN (p = 0.052)." (PMID 37712645, 2023). "Our results are consistent with the literature reporting the role of CRP in cancer-associated events." (PMID 36793395, 2023). "Taken together, these data highlight the potential value of additional CRP measurements in cardiovascular and cancer risk assessment." (PMID 37019514, 2023). "Plasma CRP levels have also shown to be useful in predicting future cardiovascular and cancer risk in the general population." (PMID 37019514, 2023). "In the present study, based on a large-scale prospective cohort study, we found elevated CRP concentration at baseline were associated with increased risk of incident cancer events during the follow-up." (PMID 36117174, 2022). "Intriguingly, our study found that among all biomarkers of AL score, higher levels of triglycerides and CRP were associated with 1.68 and 1.42 folds increased risk of cancer (triglycerides: HR = 1.68, 95% CI: 1.16, 2.43; CRP: HR = 1.42, 95% CI: 1.01, 2.01)." (PMID 35804816, 2022). "This indicated the necessity of a pan-cancer analysis to systematically evaluate the associations of CRP and cancer risk, especially in prospective studies." (PMID 36117174, 2022). "Elevated CRP, used as a surrogate marker for inflammation, was reported to be associated with many types of primary operable cancers." (PMID 36401194, 2022). "The fuzzy model takes into consideration age alongside four of the relevant biological parameters associated with the presence of cancer: age, Hemoglobin level, C-reactive protein CRP, platelet count (PLT), and alkaline phosphatase (ALP)." (PMID 35626439, 2022). "Third, physical activity is associated with lower levels of systemic inflammation by altering inflammatory cytokines or adipokines (e.g., C-reactive protein, adiponectin and interleukin-6), which are associated with a higher risk of cancer." (PMID 36510257, 2022). "A few studies compared baseline values of biochemical markers commonly associated with cancer and cancer-related stroke, and found higher mean CRP and D-dimer values, higher leukocyte counts, lower hemoglobin, and lower platelet counts." (PMID 36012933, 2022). "This study allowed us to have an umbrella view of the associations between five biomarkers linked to biological ageing (GDF-15, NT-proBNP, HbA1C, CRP, cystatin-C) and cancer and CVD risks." (PMID 34935094, 2022). "In further analysis of individual biomarkers of AL score, we found that higher levels of triglyceride and CRP were associated with increased risk of cancer, highlighting the role of metabolic dysfunction and inflammation in the etiology of cancer development." (PMID 35804816, 2022).
cancer (continued). "A report from the general Danish population, which included 10,408 participants, found that elevated levels of CRP in cancer-free individuals were associated with an increased risk of cancer of any type and possibly CRC." (PMID 36407320, 2022). "Compared with individuals at low CRP concentration, those in the intermediate and high CRP concentration had a higher risk of overall cancer, with HRs of 1.05 (95%CI: 1.02, 1.07; P < 0.001) and 1.15 (95%CI: 1.12, 1.18; FDR-adjusted P < 0.001), respectively." (PMID 36117174, 2022). "Raised CRP levels in different cancer patients have been associated with poorer survival outcomes, lower functional activity, abnormal metabolism and more extensive disease, and specifically in PDAC, elevated CPR levels reflect a more aggressive tumour." (PMID 35020761, 2022). "Preoperatively elevated serum CRP levels are associated with an increased incidence of postoperative complications in cancer patients, while serum albumin is produced in the liver and is the most abundant serum protein." (PMID 34519976, 2022). "It was the first study to assess the associations between combinations of biomarkers linked to biological ageing (GDF-15, NT-proBNP, HbA1C, CRP, cystatin-C) and cancer risk." (PMID 34935094, 2022). "This contention is supported by the findings of two large prospective cohort studies that described positive associations between elevated circulating levels of CRP and the risk of cancer of any type." (PMID 35223501, 2022). "Based on a large-scale prospective cohort study, we demonstrated a positive association between CRP concentration and overall cancer risk, as well as nine site-specific cancers." (PMID 36117174, 2022). "CRP has been identified as a diagnostic tool in assessing disease status and progression even in cancer." (PMID 36612251, 2022). "Women with pre-treatment CRP ≥5.5 mg/L had a 68% increase in overall (adjusted HR = 1.68, 95% CI 1.00–2.81, p = 0.049) and a two-fold higher cancer-specific mortality risk than those with CRP <5.5 mg/L (adjusted HR = 2.04, 95%CI 1.03–4.02, p = 0.04)." (PMID 34802721, 2022). "Inconsistent associations have been reported between CRP and cancer risk in previous prospective cohort studies." (PMID 36117174, 2022). "The main advantage of this study lies in a comprehensive analysis, including both observational analysis and MR analysis, of the associations between CRP and overall cancer risk, as well as site-specific cancer." (PMID 36117174, 2022). "In diabetic patients, serum 25(OH)D, cadmium, and CRP were associated with all-cause mortality; serum 25(OH)D was associated with cardiovascular mortality; CRP was associated with cancer mortality." (PMID 35571939, 2022). "Epidemiological studies have suggested that elevated circulating levels of CRP, as measured with high sensitivity, not only signal an epidemic of cancer, but are also associated with an increased risk of future cancer in apparently healthy people." (PMID 35752767, 2022). "The increase of serum CRP concentration was associated with incident events of overall cancer (HR = 1.02, 95% CI: 1.01–1.02 per 1mg/L increase, P < 0.001)." (PMID 36117174, 2022). "Women with a high pre-treatment CRP at a decision threshold of 5.5 mg/L had a 68% increase in overall mortality and a two-fold higher cancer-specific mortality risk compared to those with low CRP." (PMID 34802721, 2022). "High cancer recurrence risk among obese survivors can be driven by inflammatory cytokines, including C-reactive protein (CRP), Interleukins −3, −6, and −8 TNF-α." (PMID 35276833, 2022). "The associations of CRP and cancer risks became stronger by only including patients that were diagnosed within 2 years of follow-up, indicating the associations were true." (PMID 36117174, 2022). "Previously, CRF levels had been described as inversely associated with CRP values in the healthy general population, men and cancer survivors." (PMID 36614866, 2022).
cancer (continued). "Observational analyses showed higher CRP concentration was associated with increased risk of overall cancer (hazard ratio (HR) = 1.02, 95% CI: 1.01, 1.02 per 1mg/L increase, P < 0.001)." (PMID 36117174, 2022). "Compared with the low CRP group, the high CRP group was associated with higher all-cause mortality (HR = 1.65, 95%CI 1.24–2.19, P = 0.001) and cancer mortality (HR = 3.25, 95%CI 1.82–5.80, P < 0.001)." (PMID 35571939, 2022). "Several studies have reported that CRP levels gradually increase in response to chronic systemic inflammation associated with cancer cachexia in the terminal stage." (PMID 34241700, 2022). "The two studies with established inflammation were all associated with plasma C-reactive protein concentrations of 60–80 mg/L, which is commonly encountered after major surgery or in patients with advanced cancer stages." (PMID 35410365, 2022). "In particular, the mGPS, which utilises normal reference value cut-offs for albumin (≥35 g/l) and CRP (≤10 U/l), has been extensively studied and is associated with survival, quality of life, weight loss, and response to treatment in patients with cancer." (PMID 35398717, 2022). "While the association between CRP and cancer diagnosis was similar to that of ALP, the reduction in patient numbers decreased reliability of the findings." (PMID 35482741, 2022). "Increased CRP can be observed in many malignant tumors and is associated with poor prognosis of tumor patients." (PMID 35965687, 2022). "CRP is an acute-phase protein produced in hepatocytes, and a high CRP level is associated with poor outcomes in patients with cancer." (PMID 35756636, 2022). "In our sample, VO2MAX was associated with CRP, so increasing leisure-time PA and implementing exercise programs focused on improving CRF is essential in reducing CRP and, therefore, the risk of CV and mortality in cancer survivors." (PMID 36614866, 2022). "Hypermetabolism has been correlated with clinical and biological markers of cancer cachexia such as weight loss, PS ≥ 2, CRP ≥ 10 mg/L and associated with reduced survival." (PMID 35804986, 2022). "Multivariate survival analysis of CRP in patients with cancer showed that the risk of death increased by 13% per SD increase in CRP (95% CI=1.09–1.18)." (PMID 35752767, 2022). "In line with this, increased levels of CRP were also found in shift workers, indicating a progression of an inflammatory state and an increased risk of cancer." (PMID 35246220, 2022). "In this context, the pro-inflammatory cytokines, tumor necrosis factor-α (TNF-α) and interleukin (IL)-6 (a major inducer of CRP), as well as the immunosuppressive cytokine, IL-10, have all been implicated in both the initiation and development of cancer." (PMID 35223501, 2022). "Implications for cancer survivors: in case of elevation of CRP indicating cardiovascular risk, health professionals should recommend lifestyle changes to improve BCS physical condition." (PMID 36614866, 2022). "The incidence of cancer and cancer-related death was also associated with a high level of circulating IL-6, TNFα, and CRP in a five-year follow-up of elderly individuals." (PMID 36369012, 2022). "As for the location group, both in the RC and LC cancers had higher CRP/MCV values, which were associated with a worse prognosis." (PMID 34221966, 2021). "A prospective study assessing potential risk biomarkers for the development of VTE in cancer patients measured CRP and P-selectin in 705 patients with solid tumors with a follow-up of 12 months." (PMID 33807848, 2021). "The fact that plasma levels of CRP and albumin are routinely measured in cancer older patients underlines the clinical applicability of our present results." (PMID 34944774, 2021). "Its serum levels increase quickly in response to most types of inflammation, and elevated CRP levels have been reported to be associated with an increased risk of cancer." (PMID 34502325, 2021).